VEGFC (vascular endothelial growth factor C)
Diseases named in the same sentence as VEGFC in open-access papers (continued):
Sharing a sentence is not in itself a finding about the gene and the disease.
tumor (continued). "Using species-specific probes, we found that chronic stress elevates the expression of both tumour cell-derived and stromal cell-derived VEGFC in MDA-MB-231 primary tumours." (PMID 26925549, 2016). "Vascular endothelial growth factor-C (VEGF-C) is the major lymphangiogenic factor, and makes crucial contributions to tumor lymphangiogenesis and lymphatic metastasis." (PMID 27166194, 2016). "A large number of clinical studies have shown that increasing expression of VEGFC in primary tumors correlated with enhanced dissemination of tumor cells to regional lymph nodes in a variety of human carcinomas." (PMID 23593282, 2013). "Recent evidence suggests that vascular endothelial growth factor-C (VEGF-C)- dependent tumour production promotes lymphangiogenesis, while membrane-type matrix 1 metalloproteinase (MT1-MMP) is involved in the critical steps leading to carcinogenesis." (PMID 24119788, 2013). "Our data demonstrate that miR-27b originates in CSCs from CRC and acts as an important tumor suppressor and angiogenic factor by targeting VEGFC." (PMID 23593282, 2013). "Many studies have reported that VEGFC correlates with tumor growth and metastasis in a variety of cancers, including CRC." (PMID 23593282, 2013). "This is consistent with our results, which showed a relatively high loading of KDR on the principal component associated with VEGFC, NRP1, and PLXND1, which had the second highest association with triple-negative (TN) status in the all-tumor data set." (PMID 23667446, 2013). "A closer inspection of the tumor-infiltrating macrophages in TGFα-positive tumors showed that these cells express the lymphangiogenic growth factor VEGFC." (PMID 23986907, 2013). "VEGFC-knockdown repressed cell proliferation compared to the NC cells, significantly inhibited colony formation and reduced tumor growth." (PMID 23593282, 2013). "In the analysis of all tumors, this VEGFC-dominated signature (tumor cluster D) was present in 18.5% of tumors." (PMID 23667446, 2013). "Tumor lymphangiogenesis is known to promote lymphatic metastasis, and vascular endothelial growth factor C (VEGF-C) is a critical activator of tumor lymphangiogenesis during the process of metastasis." (PMID 22952986, 2012). "Vascular endothelial growth factor C (VEGF-C) has been identified as a multifaceted factor participating in the regulation of tumor angiogenesis and lymphangiogenesis." (PMID 23344023, 2012). "Vascular endothelial growth factor-C overexpression induced early metastasis and significantly increased the lymphatic vessel area in sentinel lymph nodes even before the tumor metastasis." (PMID 23076721, 2012). "Vascular endothelial growth factor-C (VEGF-C) is the most important lymphangiogenic factor produced by tumor and stromal cells." (PMID 21272377, 2011). "Increasing evidence suggests that NP2, a coreceptor for VEGFC, emerges as a potent regulator of lymphangiogenesis in embryonic vessel development, tumor lymphangiogenesis and metastasis." (PMID 21139694, 2010). "Genes promoting cancer progression (u-PAR, VEGFC, and HIF1α) and tumour suppression (VHL, RASSF1, and FHIT) of NSCLC were significantly (P<0.05) down- or upregulated after Enz treatment in H460, A549, and H1299 cells, respectively." (PMID 20736951, 2010). "It is now clear that in animal models the incidence of metastasis is increased in tumours expressing lymphatic endothelial growth factors such as vascular endothelial growth factor C (VEGF-C)." (PMID 20478045, 2010). "Recent work in animal models showed that the incidence of metastasis is increased in tumours expressing endothelial growth factors such as vascular endothelial growth factor C (VEGF-C) and VEGF-D." (PMID 14760386, 2004). "Meanwhile, tumor cell type T1 sent signals through VEGFC‐KDR interactions to meCAFs and iCAFs." (PMID 40843133, 2025).
tumor (continued). "This would imply that VEGFC-reducing proliferation/migration of MB cells could keep the tumor in a condition more prone to being attacked by antitumor immune cells." (PMID 40677711, 2025). "Alternatively, VEGFC originating from fibroblasts induces tumor cell progression from TN to PD." (PMID 40843133, 2025). "Notably, in non‐responders, T1 tumor cells were engaged in an interplay with meCAFs via VEGFC–KDR signaling (kinase insert domain receptor; VEGF receptor 2) and exclusively received FGF2–FGFR1 signals from meCAFs." (PMID 40843133, 2025). "Dual inhibition of VEGFA/VEGFC suppresses tumor growth, suggesting that combined VEGF targeting may enhance efficacy of ABCP in resistant NSCLC patients." (PMID 40843133, 2025). "Notably, it has been demonstrated that activation of the VEGFR3/FLT4/CD310 axis in tumor macrophages can promote resistance to taxanes by inducing VEGFC expression." (PMID 41459512, 2025). "Moreover, VEGFC protein expression was elevated in X‐irradiated tumour lysates compared to both P‐irradiated and control (C) tumours." (PMID 40400121, 2025). "The construction of the protein–protein interaction network provided additional insight into the functional roles of the selected genes, pinpointing LAMC2, LAMA3, and VEGFC as central nodes that could play crucial roles in tumor development and progression." (PMID 39766765, 2024). "The PROX1 transcription factor is responsible for the expression of the vascular endothelial growth factor receptor 3 (VEGFR3), which is stimulated by tumour-cell-derived VEGFC; this triggers tumour lymphangiogenesis and establishes the main route of dissemination for solid tumours." (PMID 38203852, 2024). "Meanwhile, inhibition of miR-664a-3p could significantly decrease the expression of HIF-1α, VEGFA, and VEGFC, which have been reported to act as factors that contribute to tumour angiogenesis." (PMID 38035445, 2024). "Our previous reports revealed that VEGFC is the key regulator of tumor lymphangiogenesis." (PMID 38949026, 2024). "Additionally, VEGFC, a significant driver of lymphangiogenesis produced by tumour cells and M2 macrophages, not only induces resistance to anti-angiogenics but also plays a crucial role in fibrosis through crosstalk with TGFβ." (PMID 38397987, 2024). "In addition, VEGFB and VEGFC are part of two signaling pathways with major roles in tumor angiogenesis and lymphangiogenesis." (PMID 38256218, 2024). "They discovered that mice with GBT and overexpression of the vascular endothelial growth factor C (VEGF-C) demonstrate a better response to anti-tumor therapy, such as the combination of anti-programmed death-1 protein (PD1) and cytotoxic T-lymphocyte-associated protein 4 (CTLA-4) blockade." (PMID 38317779, 2024). "Experimentally, VEGFC knockout cells fail to induce the development of experimental ccRCC in immunodeficient mice, a context that mimics immunotolerance, whereas they induce a rapidly growing tumour in an immunocompetent context." (PMID 38397987, 2024). "Since VEGFC recruits macrophages to the mammary gland during tumor development, this mechanism could also be at play during pubertal development of the mammary gland." (PMID 38218743, 2024). "Collectively, our findings indicate that STOML2 facilitates the recruitment of TRADD and sustains NF-κB activity to upregulate CCND1, VEGFC and PD-L1, which consequently leads to tumor proliferation, angiogenesis, immune escape and poorer clinical outcomes in human in CRC." (PMID 38214751, 2024). "Our findings showed the associations between the high expression of VEGFA, VEGFC, and PGF and poor prognosis across various cancers, suggesting that they may serve as risk factors for tumor progression." (PMID 37852616, 2023). "The VEGFC/VEGFR3 pathway affects tumor immunity by inhibiting T‐cell proliferation." (PMID 35832030, 2023). "In addition, TNF-α upregulated the levels of VEGFC and D2-40 in tumor tissues compared with the control group." (PMID 37124061, 2023).
tumor (continued). "The VEGFC/D-VEGFR3 axis is primarily activated by proteolysis to promote tumor-associated lymphangiogenesis and metastasis to the lymph nodes." (PMID 37803421, 2023). "Moreover, TNF-α obviously elevated D2-40 and VEGFC protein expressions in tumor tissues, promoting lymphangiogenesis and lymphatic metastasis in vivo." (PMID 37124061, 2023). "The process helps tumor cells escape immune responses, where VEGFC/VEGFR3 pathway plays a role." (PMID 35832030, 2023). "Thus, the key feature of PTX-resistant cells was the overexpression of pro-angiogenic factors such as VEGFA, VEGFC, and Ang2, known to support tumor cell growth." (PMID 36874116, 2023). "Moreover, tumor-induced lymphangiogenesis is known to play a vital role in the initial stages of cancer metastasis, andthe link between VEGFC and tumor lymphangiogenesis and metastasis has been extensively investigated." (PMID 37124061, 2023). "VEGFC is one of the most important regulators of tumour lymphangiogenesis." (PMID 35600335, 2022). "It has been found that the expression of VEGFC in tumor tissues is beneficial to tumor metastasis." (PMID 35371324, 2022). "Interestingly, the expression of claudin-3 in lymphatic endothelial cells is down-regulated by vascular endothelial growth factor C that is often present in the tumor microenvironment." (PMID 36261482, 2022). "In addition, ZKSCAN5 has been recognised as a novel critical regulator for the expression of VEGFC and contributes to tumour lymphangiogenesis." (PMID 35600335, 2022). "In addition, OCT4/VEGFC/VEGFR3/EMT signaling promoted tumor growth and intraperitoneal metastasis in a xenograft mouse model." (PMID 36336681, 2022). "M2 macrophages are considered activated tumour-associated macrophages and are known to produce inflammatory signals and express high levels of growth factors that stimulate angiogenesis and lymphangiogenesis, such as VEGFA and VEGFC." (PMID 33572413, 2021). "VEGFC promotes tumor growth and angiogenesis by activating Akt and ERK signaling pathways." (PMID 34233294, 2021). "Considering the potent effect of 1E9 antibodies on VEGFC-dependent signaling, we hypothesized that they should inhibit the proliferation of tumor cells expressing such autocrine loops." (PMID 34067671, 2021). "Additionally, EVs can promote tumor lymphangiogenesis by intercellularly transferring important lymphangiogenic factors, VEGFC and chemokines." (PMID 34552874, 2021). "Analysis with TIMER showed strong correlation between NRP1 expression and the abundance of tumor progression-related genes, MMP1, MMP3, MMP9, VEGFC, FLT4 and CXCL12 in LUSC, while there isn’t clear association between NRP1 expression and this panel of pro-tumorigenic genes in LUAD." (PMID 34168096, 2021). "Moreover, VEGFC expression in cancer cells correlates with tumor progression and poor clinical outcomes." (PMID 34067671, 2021). "The results showed that BACH1 knockdown significantly inhibited the density of CD31+ blood vessels and VEGFC expression in xenograft tumor tissues derived from mice subcutaneously injected with KYSE170‐shBACH1 cells compared with those derived from mice injected with control KYSE170‐shCtrl cells." (PMID 33932125, 2021). "Indeed, the current belief states that: (i) tumor cells produce Vascular Endothelial Growth Factor C (VEGFC), the main lymphatic endothelial cell growth factor." (PMID 33067561, 2020). "This treatment-related increase in VEGFC mRNA has previously been documented in other tumor models." (PMID 33067561, 2020). "Our hypothesis is that the initial effect of VEGFC is to reduce MB cell proliferation/migration, thus keeping the tumor in a state where it can more easily be attacked and destroyed by the immune cells." (PMID 33067561, 2020). "Finally, we addressed the molecular basis of the BACH1 and VEGFC interaction during tumor progression in the various mouse tumor models." (PMID 32132179, 2020). "This high rate of tumor growth was reduced by VEGFC expression by the cells." (PMID 33067561, 2020).
tumor (continued). "Tumor derived VEGFC (Vascular endothelial growth factor C) has been demonstrated to support metastatic expansion of primary tumors into the lymphatic vasculature in many tumor types, challenging the traditional concept of a purely passive role of the lymphatic vessels in cancer metastasis." (PMID 32370304, 2020). "Indeed, VEGFC knock-out has opposite effects on tumor growth in immunodeficient or immunocompetent mice." (PMID 33067561, 2020). "VEGFC has a critical role not only during development but also during tumor progression." (PMID 32132179, 2020). "An example is VEGFC IRES activation by hypoxia previously shown in tumor cells." (PMID 31815666, 2019). "By the way, target gene VEGFC is modified by DNA methylation to cause overexpression and the overexpression of miRNA MIR27A could induce tumor cell migration and angiogenesis in late-stage PTC cells." (PMID 31126066, 2019). "Tumor cells secreted VEGFC and activated VEGFR3 of LECs to provoke the growth of lymphatic vessels." (PMID 30131072, 2018). "For example, we observed an upregulation of VEGFC in 4T1 tumor lysates." (PMID 29976154, 2018). "Importantly, disrupting the conversation of tumor cells and LECs by interferring RNA or neutralizing antibodies to VEGFC or VEGFR3, has been shown to reduce the rate of lymph node metastasis in vitro and in vivo." (PMID 30131072, 2018). "In addition, studies demonstrate that adrenergic signaling promotes lymphangiogenesis by inducing VEGFC production by tumor cells and/or macrophages." (PMID 29479349, 2018). "Thus, we find that docetaxel increases lymphangiogenesis in tumor-bearing fat pads and this is mediated in part by VEGFC, but also by a host of other pro-lymphangiogenic cytokines likely induced by TLR4 pathway activation by taxanes." (PMID 29976154, 2018). "In addition, we show a critical role for tumour cell-derived VEGFC in the effects of stress on lymphatic vasculature." (PMID 26925549, 2016). "Additionally, the findings show that stress-induced vascular remodelling is dependent on β-adrenergic signalling to inflammatory cells, which increases tumour cell-derived VEGFC." (PMID 26925549, 2016). "Furthermore, downregulation of VEGFC expression in CC cells decelerates tumor growth and inhibits metastasis." (PMID 27409174, 2016). "While tumour COX2 levels were low in control mice, stress or isoproterenol elevated COX2 mRNA transcript levels, which were strongly associated with VEGFC mRNA levels." (PMID 26925549, 2016). "VEGFC knockdown also blocked the ability of stress to promote lymphogenous metastasis and distant metastasis, consistent with a critical role for VEGFC-dependent lymphangiogenesis in stress-enhanced tumour cell dissemination." (PMID 26925549, 2016). "In contrast, the data presented here suggest that PGE2 derived from TAMs may contribute to stress regulation of tumour cell-derived VEGFC." (PMID 26925549, 2016). "Treatment with isoproterenol also elevated tumour cell and stromal cell VEGFC expression, while BB treatment blocked the effect of stress on VEGFC expression, demonstrating the importance of β-adrenoceptor activation in stress-induced expression of this lymphangiogenic factor." (PMID 26925549, 2016). "Vascular endothelial growth factor C (VEGF-C) is a specific growth factor that targets the lymphatic system and plays a critical role in tumor growth and metastasis to lymph nodes and distant organs through the formation of new vessels in various malignancies, including GC." (PMID 23866030, 2013). "We discovered that miR-27b could block CRC cell proliferation, colony formation and tumor growth and that it functions as an angiogenesis inhibitor by targeting VEGFC and down-regulating DNA hypermethylation." (PMID 23593282, 2013). "In summary, an anti-tumor role for miR-27b and its novel target VEGFC in vivo could lead to tumor necrosis and provide a rationale for developing miR-27b as a therapeutic agent." (PMID 23593282, 2013).
tumor (continued). "Moreover, TAMs are one of the sources of vascular endothelial growth factor-C (VEGF-C), which has been linked to lymphatic dissemination of tumor cells through lymphangiogensis." (PMID 24212647, 2011). "Among the genes participating in the cascade of signal transfer in cell activated by leptin, the following ones: AKT1, STAT3, MCL1 were qualified as differentiating stage I and II and VEGFC, CCNDI the encoding genes respectively as differentiating III and IV stage neoplasm." (PMID 22363883, 2011). "Moreover, we show that u-PAR, VEGFC, and HIF1α, among other targets, are being downregulated, and the tumour-suppressor genes FHIT, RASSF1, and VHL are upregulated upon Enz treatment." (PMID 20736951, 2010). "HIF may also be involved in the inhibition of tumor lymphangiogenesis by artemisinin through suppression of vascular endothelial growth factor C." (PMID 19862332, 2009). "Moreover, LPS has been shown to increase tumor cell adhesion, invasion, and metastasis through the upregulation of the urokinase plasminogen activator (u-PA) system and the secretion of vascular endothelial growth factor-C (VEGF-C)." (PMID 40722646, 2025). "Furthermore, it appears that the expression of VEGFC could be essential to favor immune response against MB at least in the early stages of development of the tumor." (PMID 40677711, 2025). "Indeed, VEGFA/VEGFC–injection reproduced the changes observed in the tumor-adjacent lymphatics in the WT strain but did not cause fragmentation in the Y949F mutant lymphatics." (PMID 38148112, 2024). "On the other hand, recent studies have shown that VEGFC treatment with lymphatic expansion could enhance anti-tumor immunity and the efficacy of immunotherapy or radiotherapy for glioma, suggesting a dual function of the lymphatic system on tumor metastasis in a context-dependent manner." (PMID 35626729, 2022). "Additionally, VEGFC was shown to be involved in tumor proliferation, invasion, and metastasis." (PMID 33932125, 2021). "However, tumors are not homogeneous, and most authors describe the so-called “autocrine” effect of VEGFC as the effect generated locally, on a specific type of cells—especially tumor cells—bearing the receptors, by the VEGFC secreted by this very type of cells." (PMID 33067561, 2020). "Thus, besides activating VEGFC processing, overexpression of CCBE1 in CRC could also enhance the release of VEGFC to promote tumor lymphangiogenesis." (PMID 32089745, 2020). "To investigate if PGE2 may induce VEGFC in tumour cells, we treated MDA-MB-231 cells with PGE2." (PMID 26925549, 2016). "This dual regulation drives PKM2-mediated metabolic reprogramming to increase tumour glucose uptake while promoting the nuclear translocation of p-PKM2, which transcriptionally activates the lymphatic growth factors VEGFC/D." (PMID 41741407, 2026). "VEGFC, FGF1, INHBA, FYN, and AGTR1 promote angiogenesis, lymphangiogenesis, EMT, invasion, and tumor cell survival – constituting pro-metastatic signaling." (PMID 41006647, 2025). "The results showed that there were was activated signaling of TNF, VEGFC and EGFR from TMGs-high epithelial niches to endothelial cells, indicating hyperactivated angiogenesis in tumor stromal tissues and a potential response to VEGF blockage." (PMID 40216815, 2025). "A recent study using mouse models has revealed that VEGFC activates the CCL21/CCR7 signaling pathway, which promotes the activation and recruitment of naïve T cells to the tumor." (PMID 38980684, 2025). "Here, we confirmed increased expression of VEGFA, VEGFC, and VEGFD; HEV dedifferentiation; and impaired lymphocyte homing function in tumor-draining LNs (TDLNs)." (PMID 40693467, 2025). "Contrastingly, CCL21 and VEGFC gene expression, as well as CCL21 and VEGFC protein drainage to lymph nodes are important biomarkers of the SA-HFIRE-induced vascular remodeling and extent of ablation within the tumor." (PMID 39998766, 2025).